MRPL42 (mitochondrial ribosomal protein L42)
Synonyms: L31mt; MRP-L31; L42mt; MRP-L42; MRPL31; MRPS32; RPML31; HSPC204; PTD007; mL42; MRP-S32; S32MT
Tractability: Small molecule: a structure with a bound ligand is known. Antibody: its Gene Ontology location is reachable by antibodies, with high confidence. PROTAC: ubiquitination databases record sites on it; its protein half-life has been measured.
Gene: Protein-coding gene on chromosome 12 (93,467,490 to 93,516,214, forward strand). Ensembl gene ENSG00000198015.
Subcellular location: Mitochondrion
Subcellular location (Human Protein Atlas): Mitochondria; Plasma membrane
Pathways (Reactome):
Metabolism of proteins: Mitochondrial ribosome-associated quality control; Mitochondrial translation elongation; Mitochondrial translation initiation; Mitochondrial translation termination
Gene Ontology:
Molecular function: RNA binding; structural constituent of ribosome
Biological process: mitochondrial translation; translation
Cellular component: mitochondrial large ribosomal subunit; mitochondrial small ribosomal subunit; mitochondrion; mitochondrial inner membrane
Genetic constraint (gnomAD): Loss-of-function variants: 5 observed, 7.47 expected, observed/expected ratio (o/e) 0.67, 90% interval 0.35 to 1.39. That is too few expected variants to judge how well the gene tolerates losing a copy. Missense variants: 96 observed, 94.06 expected, observed/expected ratio (o/e) 1.02, 90% interval 0.86 to 1.21. Synonymous variants: 17 observed, 27.17 expected, observed/expected ratio (o/e) 0.63, 90% interval 0.43 to 0.94.
Homologues: Orthologues: macaque MRPL42 (95% identical), chimpanzee MRPL42 (92% identical), dog MRPL42 (86% identical), guinea pig Mrpl42 (82% identical), mouse Mrpl42 (76% identical), rat Mrpl42 (66% identical), rat Mrpl42l1 (63% identical).
Diseases named in the same sentence as MRPL42 in open-access papers:
MRPL42 is named in the same sentence as 11 diseases in open-access papers, as found by Europe PMC text mining. Sharing a sentence is not in itself a finding about the gene and the disease. The quoted sentences say what the papers report.
glioma (6 papers, 2018 to 2025). A benign or malignant brain and spinal cord tumor that arises from glial cells (astrocytes, oligodendrocytes, ependymal cells). "Further studies have shown that knocking down MRPL42 significantly inhibits the proliferation of U251 and A172 glioma cells, while activating apoptosis and caspase 3/7 activity." (PMID 40371222, 2025). "By analyzing the TCGA database, researchers have found that MRPL42 is significantly upregulated in glioma tissues." (PMID 40371222, 2025). "For example, knockdown of MRPL42 increased the G1 and G2/M phases and decreased the S phase in the cell cycle of glioma cells, suggesting its role in accelerating the malignant advance of gliomas." (PMID 37284202, 2023). "MRPL42 gene knockout inhibits the proliferation of glioma cells by inducing cell cycle arrest and apoptosis." (PMID 34868337, 2021). "Functionally, we silenced MRPL42 in glioma cells and revealed that MRPL42 knockdown largely blunted the proliferation of U251 and A172 cells." (PMID 29531015, 2018). "In vitro, we knocked down MRPL42 in glioma cells and the results showed that MRPL42 silencing largely blunted the proliferation of U251 and A172 cells, indicating that glioma cell survival was depending on MRPL42 expression." (PMID 29531015, 2018). "We initially noticed that MRPL42 was obviously up-regulated in glioma tissues according to the The Cancer Genome Atlas (TCGA) database." (PMID 29531015, 2018). "Based on lentivirus-mediated knockdown strategy, we found that MRPL42 reduction largely suppressed the proliferation of U251 and A172 glioma cells." (PMID 29531015, 2018). "In this study, we investigated the function of MRPL42 in glioma and found that its mRNA level was evaluated in glioma tissues." (PMID 29531015, 2018). "To investigate the role of MRPL42 in glioma, we knocked down MRPL42 using lentivirus shRNA strategy in U251 and A172 cells and examined the cell viability." (PMID 29531015, 2018). "By analyzing the Cancer Genome Atlas (TCGA) database, we first found that MRPL42 was significantly up-regulated in glioma tissues compared with normal tissues." (PMID 29531015, 2018). "By analyzing the RNA sequencing data from the TCGA database, we found that MRPL42 abundance was obviously increased in a total of 558 glioma tissues as compared with ten normal tissues (fold change = 3.24, P=1.050E-09)." (PMID 29531015, 2018). "Functional study using lentivirus knockdown strategy helped us illustrate the important role of MRPL42 in glioma that MRPL42 silencing resulted in suppressed growth of glioma cells." (PMID 29531015, 2018). "Knocking down (MRPL42) could inhibit glioma cell growth by inducing cell cycle arrest and apoptosis." (PMID 33758616, 2021). "MRPL42 downregulation could inhibit glioma cell proliferation by inducing cell cycle arrest and apoptosis." (PMID 33758616, 2021). "In the present study, we demonstrated that MRPL42 was critical for glioma cell survival." (PMID 29531015, 2018). "Here in the present study, we identified MRPL42 as a novel oncogene in glioma." (PMID 29531015, 2018). "In conclusion, our findings revealed that MRPL42 was critical for glioma cell proliferation." (PMID 29531015, 2018). "We observed an up-regulation of MRPL42 in glioma tissues by analyzing the TCGA database." (PMID 29531015, 2018). "Thus, we checked MRPL42 abundance in glioma cells and found that the mRNA level of MRPL42 was higher in glioma cells U87, U373, U251, and A172 compared with NHA cells." (PMID 29531015, 2018). "To explore whether this suppressive effect is limited to U251 cells, we silenced MRPL42 in another glioma cells A172." (PMID 29531015, 2018). "Taken together, MRPL42 is a novel oncogene in glioma and might help us develop promising targetted therapies for glioma patients." (PMID 29531015, 2018). "Therefore, MRPL42 is considered a potential oncogene in glioma." (PMID 40371222, 2025). "This suggests that MRPL42 may play an important role in the development of glioma." (PMID 40371222, 2025).
glioma (continued). "These evidences might suggest an essential role of MRPL42 for glioma progression." (PMID 29531015, 2018). "We also detected the mRNA level of MRPL42 using quantitative real-time PCR (qRT-PCR) in NHA and four glioma cell lines U87, U373, U251, and A172." (PMID 29531015, 2018).
lung adenocarcinoma (3 papers, 2021 to 2024). A carcinoma that arises from the lung and is characterized by the presence of malignant glandular epithelial cells. "In addition, MRPL42 deficiency suppressed proliferation, invasion and migration, arrested the cell cycle in lung adenocarcinoma cells in vitro, and hampered tumor growth in vivo." (PMID 38987867, 2024). "MRPL42 is activated by YY1 to promote the progression of lung adenocarcinoma." (PMID 34868337, 2021).
mastitis (2 papers, 2017 to 2024). Inflammation of breast tissue during lactation or postpartum due to an obstructed duct or infection. "These genes included CCNT1, previously associated with milk and cheese-making traits; LALBA, associated with milk production traits; MRPL42, a candidate gene for mastitis resistance; and the gene suppressor of cytokine signaling 2 (SOCS2) associated with mastitis susceptibility." (PMID 39080565, 2024).
breast carcinoma (1 paper, 2024). "The same may be possible in breast cancer, where MRPL42 also appears to play a significant role in aggressive disease." (PMID 39354291, 2024).
lymph node metastasis (1 paper, 2021). "The expression level of MRPL42 was related with the patient's tumor size and lymph node metastasis, but not with the patient's gender, age, and smoking." (PMID 33758616, 2021).
oligospermia (1 paper, 2017). Decreased number of spermatozoa in the semen. "Eight genes among 817 genes (0.01%) (ADAM32, DYNLRB2, KLHL10, RIMBP3C, SEPT12, TIMD4, TSACC and TTC25) were common between MArrest and teratospermia, and three genes among 435 genes (0.007%) (HRASLS, LIMS3 and MRPL42) were common between oligospermia and teratospermia." (PMID 29150651, 2017).
tumor (4 papers, 2021 to 2025). "In LUAD, MRPL42 is known to support metastatic properties, and is crucial for tumour growth and development." (PMID 39354291, 2024). "In the CPTAC database, the expression of MRPL42 protein in tumor tissues (n=111) was significantly higher than that in normal tissues (n=111)." (PMID 33758616, 2021). "The mRNA expression of MRPL42 in tumor tissues (n=5, 30, 40, respectively) of patients with early-stage LUAD was significantly higher than that in normal tissues (n=5, 30, 40, respectively)." (PMID 33758616, 2021). "Taking together, MRPL42 was abnormally highly expressed in tumor tissues, indicating its oncogenic role in the occurrence and development of LUAD." (PMID 33758616, 2021). "Additionally, silencing MRPL42 leads to an increase in cell cycle distribution at the G1 and G2/M phases, and a decrease in the S phase, further confirming its key role in tumor cell growth." (PMID 40371222, 2025). "We suggest that if MRPL42 expression could be therapeutically targeted through the inhibition of YY1, then the size of MRPL42-overexpressing LUAD tumours could be reduced and the presence of lymph node metastases significantly diminished." (PMID 39354291, 2024). "Additionally, expression of MRPL42 is correlated with the presence of lymph node metastases and tumour size in patient samples." (PMID 39354291, 2024). "In the Human Protein Atlas database, MRPL42 was moderately or highly expressed in tumor tissues." (PMID 33758616, 2021). "As expected, the tumor weight in sh-MRPL42 group was reduced relative to sh-ctrl group." (PMID 33758616, 2021). "Similarly, in the TCGA database, compared with normal samples (n=59), the expression of mRNA MRPL42 in tumor tissue samples (n=515) was significantly increased." (PMID 33758616, 2021). "This indicates that MRPL42 acts as an oncogene in LUAD, with its expression regulated by YY1.The expression of MRPL19 is upregulated in LUAD and is associated with lymph node metastasis, tumor differentiation, and pathological status, indicating poor prognosis." (PMID 40371222, 2025). "Moreover, depletion of MRPL42 also inhibited tumor growth in vivo." (PMID 33758616, 2021). "In vivo experiments have also confirmed that the absence of MRPL42 significantly suppresses tumor growth.Bioinformatics analysis suggests that the transcription factor YY1 may promote the transcription of the MRPL42 gene by binding to its upstream promoter region." (PMID 40371222, 2025).
cancer (2 papers, 2021 to 2024). A tumor composed of atypical neoplastic, often pleomorphic cells that invade other tissues. "From this we speculated that YY1 could positively regulate MRPL42, thereby enhancing the cancer-promoting effect of MRPL42." (PMID 33758616, 2021).
mitochondrial disease (1 paper, 2026). "Our multi-omics data confirm biallelic MRPL42 loss-of-function as the underlying cause of the fatal mitochondrial disease in our patient." (PMID 41932932, 2026).
MRPL42 also shares sentences with these, for which no sentence is quoted: schizophrenia (1 paper); teratospermia (1).